KRAS (KRas proto-oncogene, GTPase)
Diseases named in the same sentence as KRAS in open-access papers (continued):
Sharing a sentence is not in itself a finding about the gene and the disease.
colorectal cancer (continued). "The rate of protein synthesis is increased by cancer-associated mutations in colorectal cancer, such as APC (APC regulator of WNT signaling pathway) loss or KRAS (KRAS proto-oncogene) mutation." (PMID 33855169, 2021). "This is created as adiponectin reduces leucine-rich repeats containing G protein coupled receptors (Lgr5+), leading to less KRAS mutant colorectal carcinoma cases." (PMID 34842660, 2021). "Non-small cell lung carcinoma and colorectal carcinoma have the greatest number of therapies targeting KRAS G12A and KRAS Q61K or related pathways." (PMID 34525976, 2021). "Mutation in KRAS, NRAS, and BRAF has been demonstrated to be involved in initiation and progression of colorectal carcinoma." (PMID 33816307, 2021). "We present the mediator probe (MP) PCR for the quantification of the seven most frequent point mutations and corresponding wild types (KRAS and BRAF) in colorectal carcinoma." (PMID 34830896, 2021). "Reports show that miR-30b-5p inhibits human colorectal cancer by targeting KRAS, PIK3CD and BCL2 and modulates glioma cell proliferation by directly targeting MTDH." (PMID 32586272, 2020). "Somatic EGFR mutations were frequent in lung cancers, whereas somatic KRAS and APC mutations were frequent in colorectal cancers." (PMID 33193564, 2020). "An established KRAS G13D mutant colorectal cancer (CRC) patient-derived xenograft (PDX) model was treated with cetuximab." (PMID 32404198, 2020). "Paliogiannis and colleagues reported a KRAS concordance rate of 90.3% between primary tumors and metastatic sites in patients with colorectal cancer and confirmed as well a high KRAS homogeneity." (PMID 33002027, 2020). "HTC116 cells are microsatellite unstable (MSI phenotype), CIN-negative (like 10–20% of colorectal cancers), CIMP-positive, and harbor mutations in the KRAS and PIK3CA genes." (PMID 32916986, 2020). "In 2008, it was approved as a first-line treatment for EGFR-positive and KRAS wild-type colorectal cancer." (PMID 33383632, 2020). "For example, miR143 was overexpressed using OAdVs to suppress an oncogene, Kirsten rat sarcoma viral oncogene homolog (KRAS), in colorectal cancer cells and miR199 was overexpressed to address HCC." (PMID 32526919, 2020). "For example, MYCN and KRAS are prominently involved in neuroblastoma and colorectal cancer, respectively." (PMID 31992345, 2020). "Despite its high frequency in colorectal cancer (CRC), data to support specific associations between KRAS mutations in CRC and diet are sparse." (PMID 32723394, 2020). "Reovirus has been shown to preferentially replicate in and be cytopathic to colorectal cancer cells possessing an activated KRAS-signaling pathway." (PMID 32552875, 2020). "The mutation pattern of KRAS provides guidance of individualized treatment, and the KRAS wild‐type colorectal cancer patients can benefit from treatment with anti‐epidermal growth factor cetuximab." (PMID 32207862, 2020). "KRAS mutations in solid tumors appear in 90% of pancreatic cancer cases, 10%–15% of lung cancer (mainly NSCLC) cases, and 30%–40% of colorectal cancer cases." (PMID 32342665, 2020). "KRAS‐mutant colorectal cancer was found to be extremely sensitive to combined inhibition of Bcl‐2/Bcl‐xL and mTORC1/2." (PMID 32073727, 2020). "Data from the literature reported KRAS and BRAF mutations’ roles as prognostic and predictive biomarkers among patients undergoing colorectal cancer liver metastases hepatic resection." (PMID 32858990, 2020). "In the era of targeted therapy for cancer, KRAS testing is utilized in the initial diagnosis of colorectal cancer." (PMID 32329932, 2020). "Here, we analyze how a common oncogenic KRAS mutation (KRASG13D) affects PPIN structure and function of the Epidermal Growth Factor Receptor (EGFR) network in colorectal cancer (CRC) cells." (PMID 31980649, 2020). "We previously showed that mutant KRAS colorectal cancer (CRC) cells release sEVs containing Rab13 protein and mRNA." (PMID 32978434, 2020).
colorectal cancer (continued). "PCA Analysis, showed that all mutant colorectal cancer cell lines were clearly separated from the wild-type KRAS controls." (PMID 32300895, 2020). "Intracellular glutamate levels were decreased in most KRAS mutant colorectal cancer cells (KRAS G13D, KRAS G12S, KRAS G12C and KRAS G12V)." (PMID 32300895, 2020). "It has been also shown that KRAS mutations are a significant predictor of overall survival in metastatic CRC and of recurrence after surgery or radiofrequency ablation of colorectal cancer liver metastases (CLM)." (PMID 33226505, 2020). "Parallel to observations for colorectal cancer, our previous work showed that KRAS mutant subpopulations are prevalent in lung adenocarcinomas." (PMID 32898185, 2020). "One example of this is the high-quality retrospective analysis of randomized phase three clinical trial data sets, which led to the routine clinical use of KRAS as a biomarker for response to anti-EGFR therapies in colorectal cancer." (PMID 33442473, 2020). "Molecular diagnostic testing of KRAS and BRAF mutations has become critical in the management of colorectal cancer (CRC) patients." (PMID 32923312, 2020). "The KRAS K117N alteration, detected in patient NB67R5, has been shown to decrease GTPase activity although studies from colorectal cancer indicate this alteration to be less potent than mutations in codons 12 and 1322." (PMID 33384420, 2020). "Oncogenic driver mutations in KRAS represent particularly promising target epitopes due to their tumor specificity and high prevalence in PDAC, colorectal cancer (CRC), and lung cancer." (PMID 33087697, 2020). "Later studies also revealed that in KRAS mutant colorectal cancers, STAT1, CXCL10, and HLA-II are all downregulated." (PMID 32725342, 2020). "While some driver mutations are targetable, others have shown to confer resistance to standard therapy choices such as KRAS, BRAF, and PIK3CA mutations in colorectal cancer." (PMID 32760731, 2020). "The previous study has shown that BCAM plays a functional role in the metastatic spreading of KRAS‐mutant colorectal cancer." (PMID 31951095, 2020). "The mechanism of how an increase in origin licensing is mediated via oncogenic KRAS in colorectal cancer cells remains elusive." (PMID 32612138, 2020). "For example, the apoptosis inhibitor BCL-XL17 was among the factors identified to be essential for KRAS mutant colorectal cancer cells, as well as the DNA replication licensing factor CDC618." (PMID 32612138, 2020). "Among the recurrent mutations in colorectal cancers, APC and KRAS mutations were common between adenomas and carcinomas, indicative of their early occurrence during genomic evolution." (PMID 32023847, 2020). "In the human colorectal cancer cell lines, the MASI of the KRAS gene mutation has been reported to be sensitive to MEK inhibitors." (PMID 32019606, 2020). "In a small panel of FFPE colorectal cancer specimens, the mutant-enriched SLAM-MS showed reliable identification of the most common KRAS mutations confirmed by Sanger sequencing." (PMID 32214156, 2020).
colorectal cancer (continued). "KRAS is the most frequently altered gene among the three human RAS isoforms and is mutated in approximately 30–50% of colorectal cancers." (PMID 32974155, 2020). "These new experiments further support a mechanism in which cetuximab inhibits wild-type (HRAS and NRAS) signals in KRAS G13D colorectal cancers." (PMID 33153459, 2020). "Inhibition of BCAM impaired adhesion of KRAS‐mutant colorectal cancer cells specifically to endothelial cells." (PMID 31951095, 2020). "Several meta-analyses have been performed to study KRAS and BRAF mutations in melanoma, non-small cell lung cancer (NSCLC), colorectal cancer and papillary thyroid cancer." (PMID 33680376, 2020). "The most studied candidate genes are those belonging to PI3K cancer-related pathway, and KRAS in particular, due to its primary role in colorectal cancer." (PMID 32625092, 2020). "The RREB1 mRNA exhibits 3- to 20-fold higher in colorectal cancer cells harboring active KRAS than that in normal colon tissues." (PMID 32210733, 2020). "We observed a similar trend like colorectal cancer (CRC), in which an Indian cohort detected to have only 20.5% KRAS mutated patients, compared to~ 40% KRAS mutants in Western counterparts." (PMID 32552660, 2020). "In KRAS-mutant pancreatic adenocarcinomas and colorectal cancers, MASI of the KRAS gene has been associated with a poorer prognosis compared with tumors with heterozygous KRAS mutations." (PMID 32019606, 2020). "In conclusion, we provide evidence that oncogenic KRAS expression sensitizes colorectal cancer cells to inhibition of DNA replication origin licensing by suppression of the replication factor MCM7." (PMID 32612138, 2020). "Kirsten rat sarcoma viral oncogene homolog (KRAS)-driven colorectal cancer (CRC) is notorious to target with drugs and has shown ineffective treatment response." (PMID 32580297, 2020). "The levels of ATP, GTP and UMP were also reduced in most KRAS mutant colorectal cancer cells compared to their corresponding wild type." (PMID 32300895, 2020). "The best prognostic value in colorectal cancer patients undergoing surgery for liver metastases was observed based on the detection of the level of KRAS ctDNA in combination with routinely determined tumor marker CEA." (PMID 32867151, 2020). "Since then, in 2015, all patients having a resection for a diagnosis of colorectal cancer in the North East of Scotland have had the KRAS, BRAF and MSI status assessed on their surgical specimen." (PMID 32041565, 2020). "Interestingly some studies reported, as previously observed for colorectal cancer, a specific role of different KRAS somatic mutations, suggesting that a different contribute to tumor aggressiveness and treatment sensitivity could derive from different alterations in the KRAS protein structure." (PMID 32625092, 2020). "To evaluate the effect of miR-31-3p, miR-143 and miR-145 on the c-MYC expression in colorectal cancer, we deregulated these miRs in two anti-EGFR resistant cell lines: KRAS mutated (p.G13D) HCT116 and KRAS mutated (p.G12V) SW480 cell line." (PMID 32164324, 2020). "Weighted gene co-expression network analysis (WGCNA) was used to identify the hub gene in Kirsten-rat sarcoma viral oncogene homolog (KRAS) mutant colorectal cancer (CRC) patients." (PMID 33344222, 2020). "Recently, small molecules targeting KRAS G12C have entered phase 1 and 2 clinical trials for the treatment of colorectal carcinoma." (PMID 32698386, 2020). "The transforming protein of KRAS is implicated in various malignancies, including LUAD and colorectal carcinoma." (PMID 32962626, 2020). "A similar phenomenon was presented in a case report of a patient with colorectal carcinoma where a poor prognosis was observed after incomplete elimination of KRAS mutant ctDNA fragments." (PMID 32668764, 2020).
colorectal cancer (continued). "Abnormalities in KRAS-mediated differentiation and proliferation were linked to activation of the HES-1 transcription factor in colorectal carcinomas." (PMID 32974155, 2020). "We explored the association of clinico-pathological variables related to the mutational status of KRAS, NRAS, BRAF, and PIK3CA, genes that are involved in the main pathways of different solid tumors including colorectal cancer." (PMID 31036005, 2019). "As predicted, the patient’s blood sample at the time of colorectal cancer diagnosis (week 36) had detectable KRAS mutant ctDNA (2 c/mL)." (PMID 31727009, 2019). "This study reports the functional characterization of the non-canonical KRAS G12S and KRAS A59T mutations, and the novel KRAS Y137C and NRAS A11V mutations identified in Filipino colorectal cancer patient tumor samples." (PMID 31816869, 2019). "Previously, mass spectrometric characterization of KRAS expressed in pancreatic and colorectal cancer cells have shown that KRAS, like most eukaryotic proteins, undergoes N-terminal methionine excision and N-terminal acetylation." (PMID 31324887, 2019). "In line with our findings, Cheon and co-workers recently demonstrated for other KRAS mutant colorectal cancer cells a bypass mechanism of refametinib resistance to MEK inhibition involving the activation of STAT3 and MAPK triggered by MIF overexpression." (PMID 31557914, 2019). "Our experiments highlight key differences between oncogenic BRAF and KRAS in colorectal cancer and find unexpected heterogeneity in a signalling pathway with fundamental relevance for cancer therapy." (PMID 31266962, 2019). "CXCR4, SMAD4, and KRAS coexpressed with hsa-miR-224-5p were enriched in pathway of Intestinal immune network for IgA production and colorectal cancer." (PMID 31073530, 2019). "In this study, we examined horizontal transfer of mutant KRAS between colorectal cancer (CRC) cells via a direct form of cell-to-cell communication called tunneling nanotubes (TNTs)." (PMID 31247990, 2019). "Previously, we reported the anti-tumor effect of a novel synthetic miR-143 (syn-miR-143) on colorectal cancer, which miR acts on by suppressing the KRAS signaling networks in colorectal cancer cells." (PMID 30959742, 2019). "Taken together, this study uncovered an essential NEAT1/miR‐193a‐3p/KRAS regulatory axis in colorectal cancer." (PMID 30575330, 2019). "In particular, the KRAS proto-oncogene accounts for approximately 85% of all RAS mutations and has been implicated in 95% of pancreas cancers and 50% of colorectal cancers." (PMID 31413817, 2019). "The opportunity to target ERBB2/HER2 in colorectal cancer has recently emerged as it is amplified and/or mutated in 5% of CRC tumors, most often in KRAS WT tumors, which agrees with our data." (PMID 31805664, 2019). "Some prototypical examples include KRAS, NRAS, and BRAF mutations in colorectal cancers or secondary EGFR mutations in lung cancer against anti‐ EGFR targeted therapies." (PMID 30304546, 2019). "A recent study in colorectal cancer identified CCT2 as a synthetic lethal partner to mutant KRAS, which was found to be dependent on mitochondrial translation for viability." (PMID 30578123, 2019). "Regarding colorectal cancer, KRAS is involved in 24% of the biomarkers of the database, spanning 29 different variants." (PMID 31169290, 2019). "In advanced clinical practice, the oncological management of colorectal cancer requires prior knowledge of KRAS, NRAS, and BRAF status, for the design of appropriate therapeutic strategies, with more gene mutations still surfacing as potential biomarkers." (PMID 31623125, 2019).
colorectal cancer (continued). "In parallel to the imaging scans, the patient was monitored for melanoma and colorectal cancer by tracking BRAF p.V600R and KRAS p.G13D mutations in ctDNA respectively." (PMID 31727009, 2019). "Our results demonstrated the BNA-clamp PCR method with Sanger sequencing have high accuracy for the detection of KRAS, NRAS and BRAF mutations in colorectal cancer." (PMID 31711486, 2019). "In this study, we used the KRAS mutant HCT-15 colorectal cancer cell line as a model system to investigate MEK inhibitor (MEKi) mediated activation of canonical WNT signaling." (PMID 30717152, 2019). "A combination of the MEK inhibitor selumetinib and cetuximab also displayed minimal antitumor activity in KRAS mutant colorectal cancer." (PMID 31769426, 2019). "It has also been shown that PI3K/Akt/mTOR inhibitor treatments have minimal activity against advanced colorectal cancer with PIK3CA-mutations including E545K, M1043V and H1047R and that concomitant KRAS mutations frequently contribute to this resistance." (PMID 31769426, 2019). "Three types of colorectal cancer cell lines were investigated in the present research, including DLD-1(wild-type along with G13D abnormal KRAS alleles), DKO-1 (just abnormal KRAS allele) as well as DKs-8 (just wild-type KRAS allele)." (PMID 31481095, 2019). "Over 24 months, 264 specimens from colorectal cancer (CRC) patients were brought to our laboratory for KRAS, NRAS, and BRAF characterization." (PMID 31036005, 2019). "The majority of colorectal cancers are induced by subsequent mutations in APC and KRAS genes leading to aberrant activation of both canonical WNT and RAS signaling." (PMID 30717152, 2019). "In colorectal cancer, DDX3X expression has been detected, and positive associations between DDX3 and KRAS, YAP1, and SIX2 have been observed in KRAS wild-type patients." (PMID 31906196, 2019). "The present study demonstrated that KRAS and BRAF mutations induce anoikis resistance in Caco-2 colorectal cancer cells." (PMID 31545494, 2019). "In contrast, the anti-αV antibody abituzumab has shown modest activity in recurrent KRAS WT colorectal cancer, and is currently being tested in a larger randomized phase II clinical trial." (PMID 31336983, 2019). "In fact, the discordant pattern of BRAF and KRAS ctDNA was significantly correlated with the clinical response of melanoma to pembrolizumab treatment and progression of colorectal cancer noted by PET and/or CT scan." (PMID 31727009, 2019). "We studied the potential of nimotuzumab-PEG6-DM1-Low and nimotuzumab-PEG6-DM1-High to eradicate tumors in vivo using DLD-1 xenograft, a KRAS mutant (G13D) colorectal cancer model." (PMID 30800216, 2019). "We performed a comprehensive molecular profiling of 21 quadruple-wt tumors from mCRC patients enrolled in the “Cetuximab After Progression in KRAS wild-type colorectal cancer patients” (CAPRI-GOIM) trial of first line FOLFIRI plus cetuximab." (PMID 31226844, 2019). "On the molecular level, recent work using KRAS wild-type colorectal cancer cell line SW48 demonstrated that DCLK1 is transcriptionally induced by knock-in of KRAS G12D, G12V, or G13D, resulting in massive upregulation." (PMID 31467540, 2019).